TET3 (tet methylcytosine dioxygenase 3)
Diseases named in the same sentence as TET3 in open-access papers (continued):
Sharing a sentence is not in itself a finding about the gene and the disease.
liver fibrosis (continued). "Our research demonstrated that TET3 is a novel and reliable tool for predicting liver fibrosis and cirrhosis." (PMID 37076545, 2023). "In the search for a non-invasive approach to diagnose liver fibrosis, we investigated serum levels of TET3 in CLD patients at Guizhou Medical University and Affiliated Hospitals (Gui Yang, China)." (PMID 37076545, 2023). "Univariate and multivariate logistic analyses showed that TET3 levels are an independent predictor of liver fibrosis and cirrhosis (P < 0.0001)." (PMID 37076545, 2023). "miR-488-5p overexpression restrained HSCs activation and hepatic fibrosis via restraining TET3/TGF-β/SMAD2/3 signaling pathway." (PMID 36001230, 2023). "In contrast, siRNA-mediated TET3 knockdown ameliorates liver fibrosis in mice, suggesting its crucial role in the pathological development and progression of hepatic fibrosis." (PMID 33193730, 2020). "In hepatic fibrosis, TET3 promotes the activation of HSCs through suppressing the expression of 1ncRNA1A-AS1." (PMID 30534359, 2018). "TET3 is related to the development of liver fibrosis and cirrhosis." (PMID 37076545, 2023). "Thus, let-7 significantly mitigates liver fibrosis in the BDL model likely by simultaneously targeting the TET3/TGF-β and the FAS-mediated pathways in hepatocytes." (PMID 37898449, 2023). "Moreover, the expression of TET3 was remarkably higher in patients with hepatic fibrosis, based on the WB, Masson and IHC staining." (PMID 36001230, 2023). "TET3 is a novel, rapid and effective predictive tool for liver fibrosis." (PMID 37076545, 2023). "Moreover, the upregulation of TET3 was detected in multiple hepatic fibrosis models and human fibrotic liver tissues." (PMID 36001230, 2023). "Subsequently, the higher protein level of TET3 was detected in three hepatic fibrosis models." (PMID 36001230, 2023). "It is also possible that DNMT1 or TET3 regulates other lncRNAs in the process of hepatic fibrosis." (PMID 30534359, 2018). "Indeed, the deleterious role of TET3 in liver fibrosis has been suggested before." (PMID 40164757, 2025). "In our study cohort, we demonstrated that a model including TET3 and FIB-4 index exhibited a highly promising PPV for detecting stages of liver fibrosis and cirrhosis (93.50% and 100%, respectively) when compared with each diagnostic tool alone." (PMID 37076545, 2023). "Few studies have reported that TET3 played an essential role in activating TGF-β pathway, which is closely involved in the liver fibrosis." (PMID 36001230, 2023). "We identified that tet methylcytosine dioxygenase 3 (TET3), serving as a target gene of miR-488-5p, played a pivotal role in hepatic fibrosis." (PMID 36001230, 2023). "Although TET3 levels and the FIB-4 index have their own limitations, they can complement each other to increase their discriminatory power to predict liver fibrosis and cirrhosis." (PMID 37076545, 2023). "It was reported that TET3 was reduced in TGF-β1-activated human hepatic stellate cells (LX-2 cells), which played a critical role in liver fibrosis." (PMID 27141829, 2016). "We have previously identified TET3 as an epigenetic activator of TGF-β1 with the two factors regulating each other in a positive feedback fashion both in hepatocytes and HSCs promoting liver fibrosis." (PMID 37898449, 2023). "In particular, the combination of TET3 and FIB-4 index could enhance discriminatory power to predict liver fibrosis and cirrhosis when compared to TET3 or the FIB-4 index alone." (PMID 37076545, 2023). "Thus, we chose TET3 level and FIB-4 index to predict liver fibrosis and cirrhosis." (PMID 37076545, 2023). "This is further supported by the recent observation that let‐7 suppresses CCl4 and bile duct ligation‐induced liver fibrosis by inhibiting hepatocyte apoptosis and TGF‐β production through a let‐7/TET3 negative feedback mechanism in mouse hepatocytes." (PMID 40156487, 2025).
leukemia (13 papers, 2015 to 2025). A malignant (clonal) hematologic disorder, involving hematopoietic stem cells and characterized by the presence of primitive or atypical myeloid or lymphoid cells in the bone marrow and the blood. "The candidate upstream regulators for some of these genes were TNKS1BP1 (p= 1.78E-05), DNMT3A (p = 5.95E-05) and TET3(p = 2.51E-04), some genes previously associated with leukemia." (PMID 40365343, 2025). "In Haferlach leukemia samples, overexpression of TET1 and TET2 was identified, whereas TET3 downregulation was noted in Andersson leukemia samples." (PMID 39519332, 2024). "Severe deficiencies of TET2 and TET3 in HSPC lead to a loss of 5hmC of over 90%, leading to the spontaneous accumulation of DSB and further leading to the rapid progression of leukemia." (PMID 36979633, 2023). "This is further supported by evidence that TET2-deficient leukemia cells rely on residual TET activity coming from TET1 and TET3 for their proliferative advantage and survival." (PMID 35085104, 2022). "To test our hypothesis, we performed qRT-PCR to quantify the effect of both drugs on the transcription of the three isoforms, TET1, TET2, and TET3, in U937 leukemia cells." (PMID 41516186, 2025). "TET2–/– THP1 cells have a higher sensitivity to Epag compared with the nontargeting gRNA THP1 control cells, suggesting that the inhibition of residual TET activity mostly coming from TET3 may be detrimental for TET2 mutant leukemia cells." (PMID 35085104, 2022). "Recently, it was reported that the gene encoding TET2 but not TET1 and TET3 was frequently mutated, and it was identified as the relevant tumor suppressor gene, which is mutated in leukemia." (PMID 26366235, 2015).
melanoma (13 papers, 2015 to 2024). A malignant, usually aggressive tumor composed of atypical, neoplastic melanocytes. "Furthermore, reduced mRNA expression of TET2 and TET3 have been implicated in the induction of epithelial-mesenchymal transition in melanoma." (PMID 35372016, 2022). "Examining RNA-seq datasets from The Cancer Genome Atlas (TCGA) and Genotype-Tissue Expression (GTEx) databases, we observed significant down regulation of TET2 and TET3 in melanomas (n=460) as compared to healthy skin samples (n=551)." (PMID 39091741, 2024). "DNA methylation-induced silencing of TET2 and TET3 resulted in an epithelial-to-mesenchymal-like process and promoted the metastasis of melanoma." (PMID 37834158, 2023). "The expression of TET enzymes, particularly of the three members TET1, TET2, and TET3, can vary between melanocytes and melanoma in different stages." (PMID 37834158, 2023). "In contrast to DNMTs, the ten eleven translocation (TET) family of DNA demethylases (TET1, TET2, and TET3) are commonly downregulated in melanoma, and melanoma cells accordingly show reduced levels of 5hmC in their DNA compared with melanocytic nevi." (PMID 33024276, 2020). "In summary, our in vitro experiments showed that TET2 and TET3 are suppressors of the EMT-like process in melanoma and DNMT3A-mediated epigenetic silencing is one mechanism by which TGF-β induces an EMT-like process." (PMID 27852070, 2017). "Taken together, our results indicate that TET2 and TET3 are suppressors of the EMT-like process in melanoma and that the silencing of these proteins by DNA methylation is one mechanism by which TGF-β induces an EMT-like process." (PMID 27852070, 2017). "Here, we found that TET2 and TET3 play critical roles in the EMT-like process that occurs in melanoma." (PMID 27852070, 2017). "It will be interesting if, in the future, investigators dissect the signals that mediate the involvement of TET2 and TET3 in the regulation of the EMT-like process in melanoma." (PMID 27852070, 2017). "Here, our results indicate that TET2 and TET3 are epigenetically silenced by DNMT3A-catalyzed DNA methylation in the TGF-β1-induced EMT-like process in melanoma." (PMID 27852070, 2017). "Some of them such as TET1 and TET3 showed alteration in over 13%-10% of melanoma samples." (PMID 31217906, 2019). "Hence, these experiments emphasize that the epigenetic silencing of TET2 and TET3 critically contributes to the progression of melanoma and may help provide additional pertinent information for cancer diagnosis and treatment." (PMID 27852070, 2017). "In the metastatic melanoma cell line, SK-MEL-1, 5-aza treatment up regulated TET2 and TET3 expression levels, which indicates that TET2 and TET3 are silenced through DNA methylation." (PMID 27852070, 2017). "Here we report that DNA methylation induced silencing of TET2 and TET3 are responsible for the EMT-like process and the metastasis of melanoma." (PMID 27852070, 2017). "As an effector, DNMT3A senses the TGF-β signal and silences TET2 and TET3 promoters to induce the EMT-like process and metastasis in melanoma." (PMID 27852070, 2017). "As an effector, DNMT3A senses the TGF-β signal and modifies TET2 and TET3 promoters to induce the EMT-like process and metastasis in melanoma." (PMID 27852070, 2017). "We first evaluated the expression level of TETs (TET1, TET2, and TET3) in primary cultured healthy human melanocyte lines (FOM-113) and various melanoma cell lines using qRT-PCR." (PMID 25977731, 2015). "In contrast, the inferred level of expression of TET1 was lower than TET2 and TET3 and did not change between melanoma and normal skin, suggesting a less important role in regulating global 5hmC levels." (PMID 39091741, 2024). "Therefore, we analyzed expression of TET1, -2, and -3 in B16 melanoma and CT-26 tumors and found that TET2 was expressed at the highest level, with TET3 at intermediate levels and TET1 at the lowest level." (PMID 39388288, 2024).
melanoma (continued). "Consistent with our above results, TET2/3, but not TET1, were downregulated in melanoma patients in multiple GEO datasets, and TET3 expression was positively correlated with STAT3 expression." (PMID 36854755, 2023). "Furthermore, CpG methylation-induced silencing of TET2 and TET3 induced EMT-like progression and metastasis in melanoma." (PMID 29849955, 2018). "Here, in the TGF-β1-induced EMT-like process in melanoma, only TET2 and TET3 are down regulated." (PMID 27852070, 2017). "TET2 and TET3 are silenced in melanoma cells by epigenetic mechanisms triggered by TGF-β and mediated by DNA methyltransferase 3A (DNMT3A); these events play a functional role in the epithelial-to-mesenchymal transition (EMT) and in metastatic processes of melanomas." (PMID 29156643, 2017).
ovarian carcinoma (13 papers, 2016 to 2025). A malignant neoplasm originating from the surface ovarian epithelium. "Then we showed mainly TET3 gain and diploid but less deletion in ovarian cancer by copy number alteration (CNA) or mutation analysis with cBioPortal." (PMID 31656201, 2019). "TET3 CNA and gene mutation data showed that TET3 amplification or TET3 gain is the most commonly frequency in ovarian cancer, not only in the high-grade but also in low-grade serous adenocarcinoma." (PMID 31656201, 2019). "Functional plotting of TET3 indicated that TET3 mRNA expression is associated with genetic status (deletion or amplification) of TET3 in ovarian cancer." (PMID 31656201, 2019). "Furthermore, by using Kaplan-Meier plotter (K-M plotter), we evaluated that high TET3 level was associated with poor survival in ovarian cancer patients, which was validated with analysis by PrognoScan database and gene differential analyses with TCGA and GTEx." (PMID 31656201, 2019). "Loss of TET3 might result in poorer histopathological grade in ovarian cancer patients." (PMID 27141829, 2016). "Berberine, an alkaloid with antitumor properties, inhibits the Warburg effect in ovarian cancer cells by enhancing TET3-mediated demethylation via the TET3/miR-145/HK2 signaling pathway." (PMID 40191206, 2025). "Another study on ovarian cancer showed that BBR inhibited the Warburg effect via the TET3/miR-145/HK2 pathways in ovarian cancer cells." (PMID 39896297, 2025). "TET3 protein level was then detected, and consisted with mRNA reduction, TET3 protein level was increased in berberine-treated ovarian cancer cells." (PMID 33391417, 2021). "In contrast to decreased expression of TET1/2 in cancers, it was found that TET3 expression was upregulated in ovarian cancer, and its high expression was correlated with poor clinicopathological features." (PMID 34948036, 2021). "The regulatory mechanism of berberine/TET3/miR-145/HK2 pathway in the Warburg effect of ovarian cancer cells provides potential therapeutic targets in treatment of ovarian cancer." (PMID 33391417, 2021). "Down-expression of TET3 promoted cell growth, glucose consumption and lactate production in ovarian cancer cells, which was reversed by overexpression of miR-145." (PMID 33391417, 2021). "In our study, we found that TET3 was under-expressed in ovarian cancer and negatively correlated with clinical stage and pathological grade." (PMID 33391417, 2021). "We detected mRNA level of TET3 in 21 ovarian cancer tissues and 11 normal ovarian tissues by quantitative real-time PCR analysis." (PMID 33391417, 2021). "This is the first study demonstrated that elevated expression of TET3 is associated with poor clinic-pathological functions, poor prognosis, wherein TET3, which presents epigenetic changes or methylation changes, might be served as a diagnostic marker or therapeutic target for ovarian cancer." (PMID 31656201, 2019). "The result revealed that TET3 mRNA expression levels were significantly higher in ovarian carcinoma among 11 analysis with different histology (P = 0.032)." (PMID 31656201, 2019). "And we addressed that high TET3 is correlated with higher stage and poor clinicopathological features, suggesting a potentially important role of TETs in the pathogenesis of ovarian cancer." (PMID 31656201, 2019). "Subsequently, drugs inhibiting TET3 DNA amplification can rescue ovarian cancer progression and survival." (PMID 31656201, 2019). "But it is unclear that why TET3 is upregulated in ovarian cancer and what the specific mechanism is for the epigenetic regulation." (PMID 31656201, 2019). "This study firstly described the expression pattern of TET3 in ovarian cancer, and the relationship between TET3 and clinic-pathological functions based on bioinformatics." (PMID 31656201, 2019). "The TET3 expression in ovarian cancer was assessed with Oncomine database, and validated with TCGA and GTEx database." (PMID 31656201, 2019).
ovarian carcinoma (continued). "To confirm the repeatability and portability of TET3 expression pattern in ovarian cancer, we compared TET3 expression in ovarian cancer cases in TCGA and normal cases in GTEx database, as validation dataset of TET3 using this independent microarray data." (PMID 31656201, 2019). "The prognostic significance of TET3 in ovarian cancer patients was integrated by Kaplan-Meier plotter online database and PrognoScan database." (PMID 31656201, 2019). "By the meta-analysis in Oncomine database, we analyzed TET3 gene expression levels between normal and ovarian cancer tissues in four distinct ovarian cancer datasets (Hendrix Ovarian; Adib Ovarian; Lu Ovarian; Bonome Ovarian) and TCGA ovarian dataset." (PMID 31656201, 2019). "Further, GSE17260 and DUKE-OC in PrognoScan database validated the prognostic value of TET3 in ovarian cancer." (PMID 31656201, 2019). "GSE1926 also compared the carboplatin sensitive and resistant primary ovarian cancer cells from patients, and the result showed that TET3 is dramatically up-regulated in carboplatin resistant cells (P = 3.26–05, logFC = 0.48, data not shown)." (PMID 31656201, 2019). "HeLa cells transfected with TET3 plasmids were used as the positive control, and these results demonstrated that 5hmC levels differ between ovarian cancer cell types." (PMID 29156803, 2017). "TET3 protein level was then detected, and consist with mRNA reduction, TET3 protein was decreased in TGF-β1-stimulated ovarian cancer cells, indicating the potential involvement of TET3 in TGF-β1 signaling." (PMID 27141829, 2016). "Clinicopathological correlation analysis of TET3 level to ovarian cancer showed that the overall positivity of TET3 was inversely associated with the grade of differentiation of malignant cells (P = 0.024)." (PMID 27141829, 2016). "We further found that TET3 expression was decreased in ovarian cancer tissues, especially in serous ovarian cancers." (PMID 27141829, 2016). "The overall positivity of TET3 was inversely correlated with the grade of differentiation status of ovarian cancer." (PMID 27141829, 2016). "TET3 was ectopically expressed in TGF-β1-treated ovarian cancer cells to examine its effect on TGF-β1-induced EMT phenotype." (PMID 27141829, 2016). "Taken together, these results showed that TET3 was a negative regulator of TGF-β1-induced EMT in ovarian cancer cells." (PMID 27141829, 2016). "Here we report the epigenetic regulation of TET3 on miR-30d in TGF-β1-induced EMT in ovarian cancer cells, highlighting the potentiality of TET3 to be used as a prognostic biomarker or a therapeutic target for ovarian cancer." (PMID 27141829, 2016). "We further assessed TET3 expression with a human ovarian cancer tissue microarray, and finally obtained TET3 protein status in 67 ovarian cancer samples and 14 normal ovarian samples." (PMID 27141829, 2016). "In our experiments, TGF-β1 reduced TET3 in human ovarian cancer cells, and TET3 overexpression blocked TGF-β1-induced EMT via resuming the demethylation status of pre-miR-30d promoter region." (PMID 27141829, 2016). "Our results revealed that TET3 acted as a suppressor of ovarian cancer by demethylating miR-30d precursor gene promoter to block TGF-β1-induced EMT." (PMID 27141829, 2016). "TET3 was decreased in ovarian cancer and silencing of which could inhibit malignant transformation of cancer cells." (PMID 36518116, 2022). "In our study, we found for the first time that berberine can inhibit the Warburg effect of ovarian cancer cells, and berberine increased the expression of miR-145 by promoting the expression of TET3 and reducing the methylation level of the promoter region of miR-145 precursor gene." (PMID 33391417, 2021). "TET3 inhibits ovarian cancer by blocking TGF-β1-induced EMT." (PMID 34671397, 2021). "In the present study, we found that TET3 could not only promote the expression of miR-145, but also inhibit the Warburg effect of ovarian cancer cells through miR-145." (PMID 33391417, 2021).